MVB12A (multivesicular body subunit 12A)
Description:
Component of the ESCRT-I complex, a regulator of vesicular trafficking process. Required for the sorting of endocytic ubiquitinated cargos into multivesicular bodies. May be involved in the ligand-mediated internalization and down-regulation of EGF receptor.
Synonyms: CFBP; FAM125A; FLJ32495
Tractability: Antibody: UniProt places it where antibodies can reach, with high confidence. PROTAC: ubiquitination databases record sites on it; its protein half-life has been measured.
Gene: Protein-coding gene on chromosome 19 (17,405,722 to 17,433,724, forward strand). Ensembl gene ENSG00000141971.
Subcellular location: Cytoplasm; Nucleus; Endosome; Cytoplasm, cytoskeleton, microtubule organizing center, centrosome; Late endosome membrane
Subcellular location (Human Protein Atlas): Vesicles
Pathways (Reactome):
Disease: Budding and maturation of HIV virion; HCMV Late Events; Membrane binding and targetting of GAG proteins
Autophagy: Late endosomal microautophagy
Vesicle-mediated transport: Endosomal Sorting Complex Required For Transport (ESCRT)
Gene Ontology:
Molecular function: lipid binding; protein binding; ubiquitin binding
Biological process: regulation of epidermal growth factor receptor signaling pathway; viral budding; virus maturation; endosome to lysosome transport via multivesicular body sorting pathway; macroautophagy; membrane fission; multivesicular body assembly; protein transport to vacuole involved in ubiquitin-dependent protein catabolic process via the multivesicular body sorting pathway; receptor catabolic process; ubiquitin-dependent protein catabolic process via the multivesicular body sorting pathway; viral budding via host ESCRT complex
Cellular component: centrosome; cytosol; ESCRT I complex; extracellular exosome; vesicle; endosome membrane; cytoplasm; endosome; late endosome membrane; nucleus
Genetic constraint (gnomAD): Loss-of-function variants: 30 observed, 34.11 expected, observed/expected ratio (o/e) 0.88, 90% interval 0.66 to 1.19. The upper end of that interval is the gene's LOEUF score, 1.19, which puts it in group 5 of 6, group 1 being the genes least tolerant of losing a copy. Missense variants: 355 observed, 363.77 expected, observed/expected ratio (o/e) 0.98, 90% interval 0.89 to 1.07. Synonymous variants: 158 observed, 158.83 expected, observed/expected ratio (o/e) 0.99, 90% interval 0.87 to 1.13.
Homologues: Orthologues: chimpanzee MVB12A (99% identical), macaque MVB12A (99% identical), pig MVB12A (90% identical), guinea pig MVB12A (88% identical), mouse Mvb12a (82% identical), rat Mvb12a (74% identical), dog MVB12A (66% identical), tropical clawed frog mvb12a (42% identical), Drosophila melanogaster Mvb12 (26% identical), Caenorhabditis elegans mvb-12 (21% identical), zebrafish mvb12a (12% identical).
Diseases named in the same sentence as MVB12A in open-access papers:
MVB12A is named in the same sentence as 6 diseases in open-access papers, as found by Europe PMC text mining. Sharing a sentence is not in itself a finding about the gene and the disease. The quoted sentences say what the papers report.
cognitive decline (1 paper, 2025). "Higher levels of NNT, MYO15A, and GCA were protective in females; greater expression of PEPD, CTNNBL1, MVB12A, XKR8, WBP1L, and GALNT7-DT were associated with faster cognitive decline in females." (PMID 40166028, 2025).
COVID-19 (1 paper, 2022). A disease caused by infection with severe acute respiratory syndrome coronavirus 2. "Here, four hub genes including MVB12A, CHMP6, STAM, and VPS37B were considered to be involved in the core regulation of autophagy in severe COVID-19 cases." (PMID 35923698, 2022). "Therefore, MVB12A, CHMP6, STAM, and VPS37B were regarded as hub genes regulating autophagy in severe COVID-19." (PMID 35923698, 2022).
glioma (1 paper, 2021). A benign or malignant brain and spinal cord tumor that arises from glial cells (astrocytes, oligodendrocytes, ependymal cells). "For instance, MVB12A, VPS25, CHMP2A, and IST1 were significantly upregulated in glioma, whereas VPS36 and CHMP1B were significantly downregulated." (PMID 34863175, 2021). "Combining the two databases, we noticed that MVB12A, VPS25, CHMP2A, and IST1 were highly expressed in glioma." (PMID 34863175, 2021).
infection (2 papers, 2021 to 2025). The state of being infected such as from the introduction of a foreign agent such as serum, vaccine, antigenic substance or organism. "TSG101, VPS28, MVB12A, and CHMP6 were knocked down individually in 293T cells, followed by infection of the cells with replication-competent HCoV-OC43." (PMID 40407327, 2025).
MVB12A also shares sentences with these, for which no sentence is quoted: breast carcinoma (1 paper); diffuse large B-cell lymphoma (1).